IL10 (interleukin 10)
Diseases named in the same sentence as IL10 in open-access papers (continued):
Sharing a sentence is not in itself a finding about the gene and the disease.
colitis (continued). "Similarly, in DSS-induced colitis mice, S. cerevisiae strain QHNLD8L1 contributed in IL-1β reduction and IL-10 increase, with further inflammation response regulation." (PMID 39628717, 2024). "Accumulating evidence has revealed that AhR can mitigate colitis by decreasing the serum inflammatory cytokines/chemokines (e.g., TNF‐α, IFN‐γ, MCP‐1, and IL‐17), enhancing the expression of IL‐10 and IL‐22, and strengthening the intestinal epithelial cell barrier." (PMID 38882491, 2024). "Knockout mice lacking the IL-10 gene are a suitable colitis model for evaluating the efficacy of IL-10-producing Tregs in reversing the pathological condition through infusion." (PMID 39000278, 2024). "Results revealed an upregulation of IL-10 expression and a downregulation of IL-1β and IL-6 expression in T. spiralis- infected mice compared to DSS- treated mice alone during the induction of colitis." (PMID 39495798, 2024). "Serial transfer of non-inflamed (WT) mouse-adapted human microbiota to GF Il-10−/− mice induced less severe colitis than inflamed (Il-10−/−) mouse-adapted human microbiota." (PMID 39113097, 2024). "Our data show the participation of other cytokines besides IL-6, such as G-CSF, MCP-1, IL1β, and IL10, which are upregulated during DSS-induced colitis in the susceptible AIRmin SS and not in the resistant AIRmin RR mice." (PMID 36792680, 2023). "Conversely, serum levels of IL-10, an anti-inflammatory cytokine acting as a negative regulator in colitis, were increased by ECE." (PMID 38138587, 2023). "The regulation of the immune response in the gut-draining lymph nodes was also affected by the MLT treatment of colitis, with an important increase in the frequency of regulatory T cells, despite a reduced CD3+CD4+ population producing the suppressor cytokine IL-10." (PMID 36838425, 2023). "Mice deficient in IL-10 develop spontaneous colitis if they are not kept in a germ-free environment, and this colitis improves when IL-10 is administered." (PMID 37512497, 2023). "Furthermore, one study demonstrated that IECs produce high amounts of IL-10 via CD1d engagement-induced STAT3 activation, suppressing Oxa-induced iNKT cell-mediated colitis." (PMID 38274786, 2023). "In addition, in dextran sulfate sodium-induced colitis mice, Bifidobacterium not only downregulated levels of IL-6 and TNF-α, but also upregulated level of IL-10." (PMID 35918555, 2023). "In a mice model of colitis, supplementation with penta-O-galloyl-β-D-glucose inhibited colon shortening and myeloperoxidase activity, reduced the activation of NF-κB and levels of IL-1β, TNF-α, and IL-6, but increased IL-10 levels." (PMID 36829984, 2023). "In coptisine chloride therapy for colitis, coptisine chloride significant suppresses mRNA expression, releases of pro-inflammatory cytokines (TNF-α, IFN-γ, IL-1β, IL-6, IL-17) and enhances the mRNA expression level of IL-10, an anti-inflammatory cytokine." (PMID 36859380, 2023). "Using IL10−/− mice, we found that NSAID aggravated colitis in AIEC-colonized animals." (PMID 36656595, 2023). "In our study, L. sakei CVL-001 administration led to decreased gene expression levels of pro-inflammatory cytokines, such as IL-1β, TNF-α, and IL-6, and increased gene expression levels of anti-inflammatory cytokines, such as IL-10, against DSS-induced colitis." (PMID 37317332, 2023). "mediated IL-10 and IL-22 production in a DSS-driven model of anti-CTLA-4-mediated colitis." (PMID 36622383, 2023). "The actions of IL-10 from Tregs effectively restrict the development of colitis through specific suppression of Th17 cells, rather than Th1 and Th2 cells." (PMID 38107848, 2023). "Additionally, IL-1β concentration in DSS-induced mice with colitis was significantly reduced by S. cerevisiae QHNLD8L1 (p < 0.05), and IL-10 concentrations were significantly increased by S. boulardii CNCMI-745 and S. cerevisiae QHNLD8L1 (p < 0.05)." (PMID 37047694, 2023).
colitis (continued). "Here, we show that low dietary fiber promotes bacterial erosion of protective colonic mucus, leading to lethal colitis in mice lacking the IBD-associated cytokine, interleukin-10." (PMID 36993463, 2023). "Under these circumstances, the colitis in the RAG mice is presumably linked with both the passage of MMTV infection and lack of IL-10 activity." (PMID 36869359, 2023). "Furthermore, PELNs demonstrated the ability to suppress the expression of pro-inflammatory cytokines (IL-6, IL-12, IL-1β, and TNF-α) and MPO, and increase the levels of the anti-inflammatory cytokine IL-10, thereby alleviating DSS-induced colitis in mice." (PMID 37653406, 2023). "We also note that both cohorts of Il10−/− mice colonized with either FMT1 + 7 E. coli or FMT2 + 7 E. coli developed high histologic inflammation scores at 2.38 ± 0.10 and 2.62 ± 0.19 respectively (displayed as mean ± SEM), characteristic of this colitis model." (PMID 37214858, 2023). "Further research found that only 10% of IL-10 and cGAS dual-gene knockout mice formed intestinal polyps, indicating that the cGAS-STING signaling pathway exerts an indispensable role in IL-10 related colitis in mice." (PMID 37781360, 2023). "In this study, the oxidative injury caused by colitis preceded the inflammatory damage, once the levels of MPO, TNF-α, and IL-10 did not change." (PMID 37577725, 2023). "A. muciniphila has both protective and pathogenic effects, depending in part, on the degree of colonization of the host in multiple intestinal inflammatory models, including IL-10 colitis, radiation and methotrexate intestinal injury, Salmonella typhimurium, and DSS colitis." (PMID 36413219, 2023). "Expression of NF-κB, TLR4, Myd88, and downstream molecules such as TNF-α, IL-6, and IL-1β was effectively reduced by SGP-H, which improved the secretion of anti-inflammatory cytokines including IL-20 and IL-10 in the colon tissue and serum of DSS-induced colitis mice." (PMID 37836386, 2023). "They showed that it could reduce MDA, NO, MPO, hydroxyproline, TNF-α, IL-1β, IL-6, iNOs mRNA, COX-2 mRNA, IFN-γ mRNA, Bcl-2-associated X protein (Bax), Caspase-1, NF-kB and IκBα and increase IL-10, SOD and GSH in an in vivo model of TNBS-induced colitis." (PMID 36677021, 2023). "Exosomes from hucMSCs reduced the expression of the proinflammatory cytokines TNF-α, IL-1β and IL-6 in the colon in IBD mice, increased the expression of the anti-inflammatory cytokine IL-10 and attenuated the inflammatory response, thereby alleviating DSS-induced colitis in mice." (PMID 36045437, 2022). "IL-10 inhibited IL-22 secretion by macrophages and T cells, and spontaneous colitis was prevented in mice lacking IL-10 and IL-22." (PMID 36012618, 2022). "We used wild-type animals (IL-10+/+) as recipients because they do not develop colitis when colonized with H. hepaticus." (PMID 35900107, 2022). "can facilitate the development of Th1‐skewed IBD‐like colitis in IL‐10−/− mice, whereas no overt inflammation was detected in immune‐competent wild‐type B6 mice despite Th1 induction in the gut." (PMID 35244953, 2022). "Also, chromium supplementation improved histological findings, upregulated IL-10, and downregulated TNF-α, and IFN-γ in experimental colitis." (PMID 36570124, 2022). "Previous works demonstrated either a crucial role of IL-10 for the anti-inflammatory effect of IL-27 in a model of colitis or that IL-10 was not required for the suppression of Th17 cells in the context of experimental autoimmune encephalomyelitis." (PMID 36818477, 2022). "IL-10 knockout mice have lower intestinal VDR expression and develop spontaneous colitis." (PMID 36076980, 2022). "In colitis models, oral GDNPs 2 administration increased IEC survival and proliferation, decreased pro-inflammatory cytokines (TNF-α, IL-6, and IL-1), and increased anti-inflammatory cytokines (IL-10 and IL-22)." (PMID 36298592, 2022).
colitis (continued). "While reduced TNF expression is consistent with the immunomodulatory effects of HF reported in colitis, it is unclear why levels of IL-6 and IL-10 are not similarly affected." (PMID 35296081, 2022). "The strain activates intestinal CD103+ DCs through the TLR2/MyD88 pathway to generate IL-10 and induce IL-10-secreting type 1 regulatory T cells in the colon, which in turn induces IL-10 and TGF-β, weakening Th1 and Th2 cells function and ameliorating the colitis." (PMID 36389768, 2022). "It has been shown that MSCs restrain the development and activation of Th1 and Th17 cells by producing anti-proinflammatory factors, such as HLA, IL-10, TGF-β, and PGE2, and boost T cells and suppress B cells proliferation by promoting the expression of CD40, IL-6, IL-10, and TGF-β in colitis." (PMID 35990688, 2022). "IL‐10 therapy was shown to be protective against colitis progression in many animal studies with no obvious side effects reported." (PMID 35593111, 2022). "Colitis rats supplemented with 12 mg CAP/kg bw for 4 weeks decrease serum IL-6 levels and protein expression of TRPV1 and TRPA1 in the colon, and increase serum SOD and CAT activities and colonic IL-10 levels." (PMID 35269566, 2022). "In our colony, β7-sufficient IL-10−/− mice do not exhibit spontaneous colitis until after 16 weeks of age, which is often manifested clinically by rectal prolapse." (PMID 34433904, 2022). "(540 mg/kg) could not only promote BMSC homing to the injured tissue and regulate cytokines such as IL-6, IL-10, IL-17 A, and TGF-β for preventing TNBS-induced rats colitis but also promote the migration of IEC in vitro and influence multiple genes." (PMID 36160392, 2022). "However, c-Cbl deficiency leads to activation of noncanonical NF-κB subunit RelB during mannan stimulation, which suppresses canonical NF-κB subunit p65-mediated il10 transcription, thus eventually exacerbating DSS-induced mouse colitis." (PMID 35619716, 2022). "Furthermore, bone marrow mesenchymal stem cells (MSC) reduced severity of colitis through secretion of TSG6, facilitating the accumulation of IL‐10‐producing macrophages." (PMID 35593111, 2022). "Although colonic anti-inflammatory cytokine IL-10 levels were not significantly different between the colitis and the control rats, the CAP treated group significantly increased colonic IL-10 levels compared to the U group (p < 0.05)." (PMID 35269566, 2022). "Although continuous administration of IL-10-expressing probiotics has been successful in treating preclinical models of colitis, this therapy has not successfully translated to humans, perhaps due the inability of chassis to survive in the luminal environment." (PMID 35931082, 2022). "We defined this macrophages subtype induced by L. johnsonii as CD206+ macrophages.IL-10 Taken together, L. johnsonii could activate intestinal CD206+ macrophages, thus promoting the secretion of IL-10 to relieve colitis." (PMID 36398889, 2022). "Germ-free IL-10−/− mice showed no proof of colitis or related immune system activation, suggesting the critical role of gut microbiota in IBD pathogenesis." (PMID 35662934, 2022). "Furthermore, in mice with DSS-induced colitis, FXR activation decreases local IL1β and increases systemic IL10 expression." (PMID 35807844, 2022). "In a TCR-aKO model of spontaneous colitis, it was also shown that MLN CD1d+IgM-producing B-cells could suppress intestinal inflammation through the production of IL-10." (PMID 35163775, 2022). "Tregs secrete IL-10 and TGF-β, which protect against colitis by suppressing the immune response." (PMID 35308140, 2022). "Several research works supported that IL-10 is highly relevant to IBD, and IL-10−/− mice would spontaneously develop colitis, which may be related to the production of IL-22." (PMID 36176442, 2022).
colitis (continued). "In addition, HD-DCs were found to modify the anti-colitic CD4(+) T cells with the help of IL-10, and transfer of HD-DCs suppressed DNBS-induced colitis through activation of recipient IL-4 receptor-α." (PMID 36558772, 2022). "Considering that THBS1 could trigger IL-10 production in macrophages, we speculated that THBS1 might participate in MSC-mediated effects on colitis." (PMID 35371051, 2022). "In contrast, A parvulum monocolonized germ‐free (GF) Il10−/− mice did not develop significant colitis, suggesting that other microbes, or their metabolites, are required for A parvulum–driven colitis." (PMID 35244953, 2022). "Oral administration of synthetic ODN (ID35) derived from L. rhamnosus attenuated colitis, and a synthetic ODN derived from Streptococcus thermophilus NCDO 573 (commonly found in fermented milk products) increased IL-10 expression and proportion of CD4+CD25+ Treg in murine splenocytes." (PMID 35529463, 2022). "Dietary supplementation with CLA improved DSS colitis in mice by upregulating colonic IL-10, although Tregs were not directly examined." (PMID 35529463, 2022). "We show here that infection of IL-10−/− mice with the GBS but not the colitis isolate led to sciatic nerve inflammation and abnormal gait and hind limb movements, with character and timing consistent with this syndrome in humans." (PMID 35442154, 2022). "Overall, 6 IL-10−/− mice (40%) receiving ethanol as well as 4 animals (60%) receiving no additive developed signs of severe colitis and had to be removed from the study due to reaching a single end point score of 2 or a cumulative score of ≥3." (PMID 35163137, 2022). "Collectively, MSC-derived THBS1 could induce IL-10-producing B cells, which contributed to MSC-mediated therapeutic effects on colitis." (PMID 35371051, 2022). "In IL10−/− mice, the HSD exacerbated colitis compared with the LSD." (PMID 36419796, 2022). "In a chemical-induced mouse model of colitis, L. fermentum CQPC04 reduced TNF-α, IFN-γ, IL-1β, IL-6, and IL-12, and increased IL-10 release in serum; it also downregulated NF-kB and up-regulated IL-10 expression in colon tissue." (PMID 35408849, 2022). "In this study, CD4+CCR7+/− cells in mice with DSS-induced colitis were overactivated, and their subsets CD4+CCR7+IL-17A+ and CD4+CCR7−IL-17A+ increased significantly, while CD4+CCR7+IL-10+, CD4+CCR7−IL-10+, CD4+CCR7+Foxp3+, and CD4+CCR7−Foxp3+ decreased significantly." (PMID 35832382, 2022). "Analogous to the colitis and CAC incidence in humans, GI-pathogenesis in Il10-/- mice is dependent on environmental factors and follow a multi-hit model of carcinogenesis, that may involve colonic epithelial and other cell types, such as immune cells." (PMID 36584137, 2022). "Finally, to evaluate efficacy of (+)-JQ1 in vivo, we treated Il10-/- with (+)-JQ1 following colonization with fecal slurries and determined (+)-JQ1 results in a mild reduction in colitis severity." (PMID 35401533, 2022). "By contrast, the expression of Il1β, Ifng, and TNF-α (Tnf) was significantly decreased by L. reuteri treatment during DSS-induced colitis (p < 0.05) without affecting Il6 or Il10 levels (p > 0.05)." (PMID 35320932, 2022). "Additionally, this study also emphasizes that colitis and CAC incidence in Il10-/- mice are dependent on radiation quality which has implications for understanding space radiation-induced CAC and overall CRC risk among astronauts." (PMID 36584137, 2022). "In summary, our data indicate that immunization with the individual recombinant protein of T. spiralis- rTsSp ameliorates the DSS-induced colitis in mice by decreasing the infiltration of macrophages, reducing the production of TNF-α and inducing the expression of IL-10." (PMID 33995396, 2021). "Pretreatment of rats with telmisartan reduced TNBS-induced colitis decreased the disease severity and suppressed the inflammatory response by attenuating the function of TNF-α, prostaglandin E2, and Myeloperoxidase and restoring IL-10." (PMID 33628160, 2021).
colitis (continued). "The activation of CD40 is believed to be important for IL-10+ Breg generation as part of cognate interactions with activated T cells, as B cells lacking CD40 are unable to inhibit T cell activation and to protect mice from EAE or colitis." (PMID 33995344, 2021). "The lack of increased Il33 expression Il10−/− mice with colitis stands in stark contrast to the increased Il33 expression consistently observed in human UC7–10,17." (PMID 33953267, 2021). "Interestingly, we observed that colonization of mice with A. pulmonis led to impaired intestinal mucous layer and thus translocated into mAT and exacerbate colitis both in the DSS-induced colitis model and in the Il10−/− mouse model." (PMID 34814945, 2021). "Indeed, inoculation with MSCs has been described to expand IL-10+ Bregs in EAE, murine colitis, graft vs. host disease (GVHD), and allograft transplantation." (PMID 33995344, 2021). "Summary of studies investigating the role of lack of IL-10 on the development of colitis and microbiota composition." (PMID 34603258, 2021). "IL-10-knockout mice did not develop spontaneous autoimmunity but rather immune dysregulation at the body’s environmental interfaces in the form of colitis and lung inflammation." (PMID 34335631, 2021). "Although p40phox−/− mice did not develop worsened colitis, higher IL‐10 levels were observed in MLN cells and splenocytes isolated from infected p40phox−/− mice compared with wild‐type mice." (PMID 33780601, 2021). "In addition, mice with DSS-induced colitis exhibited a significant decrease of IL-10 in serum; conversely, LSE treatment significantly relieved inflammatory responses by enhancing IL-10 level (P < 0.05)." (PMID 35059326, 2021). "Finally, we inferred that the mechanism involves both IL-10 and TGF-β based upon the inability of ET to alleviated colitis when OVA TCR enriched T cells came from IL-10 and TGF-β knockout mice." (PMID 33717186, 2021). "This indicates that IL-10 was not necessary for ET to block systemic immune responses but is necessary in the gut for ET to alleviate colitis." (PMID 33717186, 2021). "We found that ET could alleviate colitis in the adoptive T cell transfer model of colitis if TGF-β and IL-10 were present but Foxp3+ Tregs were dispensable." (PMID 33717186, 2021). "IL-10(−/−) mice were shown to develop spontaneous colitis in the presence of intestinal microbiota; in addition, disruption or inhibition of PTEN was found to increase the severity of colitis and influence colitogenic bacteria in these mice." (PMID 34140896, 2021). "The piroxicam-induced alteration of the epithelium integrity sufficient to favor bacterial translocation, elicits an immune response that, in the absence of the immunoregulatory activity of IL-10, leads to colitis." (PMID 34299013, 2021). "The increase of Il-10 and Tgf-β, as anti-inflammatory cytokines, in the early days of DSS-induced inflammation has been described in a previous study, and their expression indeed decreased with the progression of colitis." (PMID 34070845, 2021). "In case of anti-inflammatory cytokine, IL-10, the levels were significantly (P < 0.05) low in the colonic homogenate of DSS colitis mice group (0.731 ± 0.20 pg/ml/mg protein) compared to the non-colitis group (1.28 ± 0.30 pg/ml/mg protein)." (PMID 34539597, 2021). "IL-10−/− mice reared under Helicobacter-free, specific-pathogen-free (SPF) conditions develop colitis that resembles human IBD when colonized with H. hepaticus, and this intestinal inflammation is associated with alterations in gut microbiota community structures." (PMID 34126769, 2021). "In accordance with other studies, we showed that colitis induction resulted in a significant increase in the level of proinflammatory cytokines (IL-1β, TNF-α, IL-6, and IFN-γ) and decreased the anti-inflammatory cytokine IL-10 in colon tissue." (PMID 33995942, 2021).